FHIT (fragile histidine triad diadenosine triphosphatase)
Diseases named in the same sentence as FHIT in open-access papers (continued):
Sharing a sentence is not in itself a finding about the gene and the disease.
tumor (continued). "If this is the case, FHIT methylation could help determine if surrounding tissue (which macroscopically appears normal) may be susceptible to transformation and the spreading of the tumor." (PMID 35663592, 2021). "Therefore FHIT-deficient preneoplastic cells survive carrying low levels of oxidative DNA damage that may contribute to increased mutation burden and ultimately neoplasia." (PMID 24901304, 2014). "In general, in tumours (lung and oesophagus) associated with environmental carcinogens, alterations in the FHIT gene occur early in cancer development, but are thought to be a late event in other cancers and possibly associated with cancer progression to more aggressive neoplasia." (PMID 14760383, 2004). "The convergence of tumor suppression (FHIT, FAM107A), metabolic reprogramming (PDHB), and immune/signaling (PTPRG, FAM3D) genes within a single genomic region suggests a potential resistance-associated haplotype block." (PMID 42302616, 2026). "Recent studies have shown that the Fragile Histidine Triad Diadenosine Triphosphatase (FHIT), a tumor suppressor gene, binds Ap4A, although with lower affinity compared to Ap3A, hydrolysing it into ATP and AMP." (PMID 40807231, 2025). "The synthetic lethality of GSK3β and FHIT has been validated in multiple FHIT-isogenic cell panels and in tumor xenograft models in vivo." (PMID 39762409, 2025). "Tanshinones have been shown to induce apoptosis in the HCT116 tumor cell line by targeting diadenosine triphosphate (Ap3A) hydrolase, a member of the human fragile histidine triad (FHIT) protein family." (PMID 39859562, 2025). "Another studied gene is the fragile histidine triad (FHIT), one of the most frequently altered genes in human neoplasia." (PMID 40423084, 2025). "Although the molecular functions of FHIT in cancer have been investigated for decades, the mechanisms of its tumor suppressive effects remain elusive." (PMID 39762409, 2025). "FHIT was the only gene that resulted overmethylated, coherently with its tumor suppressor function with roles in apoptosis and prevention of the EMT29." (PMID 38291083, 2024). "HSP60 can induce apoptosis through promoting the maturation of caspase 3, interacting with a tumor suppressor - fragile histidine triad protein (FHIT)." (PMID 37087461, 2023). "The human fragile histidine triad (FHIT) gene is a tumor suppressor gene, and heterozygous deletion (LOH), homozygous deletion, and abnormal expression of the FHIT gene have been implicated in several types of human malignancy." (PMID 37749550, 2023). "The product of the FHIT gene is at least partially lost in most human cancers, indicating some function as a tumor suppressor." (PMID 37634038, 2023). "This leads to the re-expression of methylation-silenced tumor-suppressor genes, such as fragile histidine triad protein (FHIT), CDKN2A, cadherin-13 (CDH13), cadherin-1 (CDH1) and Ras Association Domain Family Member (RASSF1A) both in vitro and in vivo." (PMID 37047090, 2023). "We recently identified another mechanism of HER2 activation, assessed by HER2 phosphorylation (pHER2), and regulated by fragile histidine triad (FHIT), a tumor suppressor frequently lost in NSCLC." (PMID 36544755, 2022). "The current study results revealed the upregulation of four genes including ADAMTS18, CDKN2B, and FHIT as tumor suppressors and WNT5B as an oncogene in the patients." (PMID 35176183, 2022). "FHIT is a tumor-suppressor gene, which is low expressed in most (possibly all) cancer types and can regulate the production of reactive oxygen species and apoptosis in cancer cells." (PMID 36110943, 2022). "LOH in the 3p14.2 locus has been implicated in the pathogenesis of gallbladder carcinogenesis by inactivating the fragile histidine triad (FHIT) tumor-suppressor gene." (PMID 35204432, 2022). "WWOX and FHIT are tumor inhibitor genes located in common chromosomal fragile sites FRA3B and FRA16D, respectively." (PMID 35250573, 2022).
tumor (continued). "We performed RNA sequencing analysis on tumor cells isolated from NSCLC (n=12) according to FHIT/pHER2 status and a functional analysis of differentially regulated genes." (PMID 36544755, 2022). "FHIT overexpression, confirmed by qPCR, resulted in a significant reduction in tumor volume and weight." (PMID 34368151, 2021). "Given that FHIT is a strong tumor suppressor and considered an early hit in the development of cancer, we examined the status of FHIT in HTLV-I associated diseases." (PMID 34092254, 2021). "FHIT gene is a prominent member of the histidine triad gene family and is considered a tumor suppressor gene." (PMID 33732167, 2021). "The top SNV of CFA20 locus lies in an intron of fragile histidine triad diadenosine triphosphatase (FHIT), a tumor suppressor involved in apoptosis and prevention of epithelial-mesenchymal transition." (PMID 33793571, 2021). "Three tumor suppressor genes residing on the most active sites of this type are Fragile Histidine Triad Diadenosine Triphosphatase (FHIT) at FRA3B, WW Domain Containing Oxidoreductase (WWOX) at FRA16D and Parkinson Disease-2 (PARK2) at FRA6E." (PMID 34204827, 2021). "One of the proteins significantly related to tumor progression is fragile histidine triad protein (FHIT), a protein that has been proven to have suppressor properties." (PMID 33920347, 2021). "Strikingly, FHIT methylation was not only found in tumorigenic T-cells, but also in cells and tissue of non-tumor origin." (PMID 35663592, 2021). "Abnormal methylation or aberrant expression of FHIT has been shown to influence tumor cell proliferation, migration, invasion, and metastasis in a variety of cancers." (PMID 34368151, 2021). "FHIT gene is a tumor suppressor located in the most common fragile site at human chromosome 3p14, FRA3B." (PMID 32545680, 2020). "Exonic deletions were detected in the PPP2R5A, FHIT, LRP1B, and OPCML tumor suppressor genes, as well as in genes implicated in cellular proliferation (CCNB1, ANAPC5, PIK3C2A) and DNA repair (SMARCA5)." (PMID 30836646, 2019). "The most frequently expressed and best-characterized CFSs in the human genome are FRA3B and FRA16D, which harbour the tumour suppressor genes FHIT and WWOX, respectively." (PMID 29695617, 2018). "We detected significant downregulation of FHIT, a tumor suppressor repressing canonical Wnt signaling by inhibition of β-catenin, whose activity is commonly impaired in preneoplastic lesions." (PMID 28137721, 2017). "First, these alterations can occur early in the preneoplastic process and would appear as clonal alterations in a tumor, just as alterations within the fragile FHIT locus are clonal in cancers and cancer cell lines." (PMID 29254236, 2017). "Q-values determined by reanalysis of the GISTIC database identified several CFS-Gs in this category, including WWOX (1.24E-265), LRP1B (1.85E-196), PARK2 (1.02E-149), and FHIT (8.70E-72), emphasizing their significant roles as tumor suppressors." (PMID 27977694, 2016). "As a tumor suppressor, FHIT’s role in the DDR is mainly guarding genome integrity and regulating apoptosis." (PMID 27977694, 2016). "Several evidences pointed at FHIT as a tumor suppressor gene; in fact, its genetic ablation in mice results both in an increase of spontaneous tumors and in a much higher susceptibility to develop carcinogen-induced tumors than wild-type counterparts." (PMID 27166255, 2016). "FHIT also appears to act as a tumour suppressor in several types of cancer, and its abnormal function has been linked to cancers of the digestive tract." (PMID 27666579, 2016).
tumor (continued). "Ectopic expression of FHIT inhibited tumor growth in both in vitro and in vivo models and resensitized radioresistant cancer cells to irradiation by restoring Chk2 phosphorylation and G2/M arrest." (PMID 27977694, 2016). "A recent report demonstrated that FHIT regulates microRNA expression and modulates tumor progression by controlling epithelial–mesenchymal transition genes." (PMID 27977694, 2016). "Taken together, these findings reveal a multifaceted role for FHIT as a tumor suppressor, including multiple functions in the DDR, defining it as an important guardian of the preneoplastic genome." (PMID 27977694, 2016). "As an identified tumour suppressor gene, FHIT is positioned on the third chromosome (3p14.2), which contains the majority of the active fragile sites of the human genome, as well as numerous chromosomal abnormalities." (PMID 25436004, 2015). "The loss of heterozygosity (LOH) of 3p loci, including FHIT, VHL, and RASSF1A (known tumor suppressors), has been confirmed in ESCC, and loss of FHIT has been reported to be associated with poor prognoses." (PMID 26465158, 2015). "The specific function of the FHIT protein is still unclear, but studies have demonstrated the role of the FHIT gene in tumour suppression." (PMID 26448938, 2015). "The fragile histidine triad (FHIT) gene is a tumor suppressor gene involved in various types of human cancers." (PMID 25875960, 2015). "Further, the CpG that showed the strongest association withlead in erythrocytes was situated in the fragile histidine triad gene(FHIT), a tumor suppressor gene located in a common fragile site that canbe rearranged due to exposure to carcinogens." (PMID 29492281, 2015). "Next, we tested the role of FHIT in tumor growth and radiosensitivity in an in vivo xenograft mouse model." (PMID 25460508, 2015). "WWOX and FHIT have long been known to reside at common fragile sites and have been demonstrated to act as suppressors of tumor development by gene knockout mouse models." (PMID 26375816, 2015). "FHIT has been reported to be involved in several tumor-suppressive processes, such as enhancing apoptosis and inhibiting tumor growth." (PMID 25460508, 2015). "They observed significantly decreased expression of FHIT in tumor samples with methylated FHIT gene using semi-quantitative RT-PCR whereas the unmethylated samples showed FHIT expression at high levels." (PMID 26198328, 2015). "Ectopic expression of FHIT inhibited tumor growth in both in vitro and in vivo models, while also resensitizing radioresistant cancer cells to irradiation, by restoring Chk2 phosphorylation and G2/M arrest." (PMID 25460508, 2015). "The methylation of RAR-β and FHIT was found less frequently in the central and peripheral parts of the tumor." (PMID 24782031, 2014). "A number of recent reports have also correlated BC development with changes in the FHIT gene which similarly to WWOX is located in a fragile site (FRA3B) and has again been linked to tumour development." (PMID 24955146, 2014). "The tumor suppressor genes assessed were fragile histidine triad (FHIT), WW domain-containing oxidoreductase (WWOX), fused in sarcoma-1 (FUS1) and phosphatase and tensin homolog (PTEN)." (PMID 25024751, 2014). "The authors conclude that tyrosine 114 is critical for the formation of the FHIT-substrate complex and subsequent tumor suppressor signaling via ROS induction and activation of Caspase-dependent apoptosis." (PMID 24901304, 2014). "Interest in other proteins that interact with FHIT and mediate apoptotic pathways supporting its tumor suppressor function led to the discovery of FHIT involvement in the response to oxidative stress." (PMID 24901304, 2014). "Ectopic expression of the miR-29 family in lung cancer cells restores expression of methylation-silenced tumor suppressor genes, including fragile histidine triad (FHIT) and WW domain containing oxidoreductase (WWOX)." (PMID 24348513, 2013).
tumor (continued). "Majority of the cases with methylated FHIT gene were tumor stage 3 (70%) and moderately differentiated histological grade (65%)." (PMID 23573237, 2013). "As a consequence, exogenous FHIT restoration in FHIT-null cancer cells acts synergistically with paclitaxel in triggering apoptosis in vitro and tumor regression in vivo." (PMID 24223161, 2013). "Our data indicate that FHIT protein is expressed in normal fibroblasts, whereas it is much reduced in both in vivo and in vitro tumours." (PMID 22424615, 2012). "The anti-FHIT polyclonal antibody was used to stain histological sections of 9 BPV positive tumour samples and 1 normal skin sample." (PMID 22424615, 2012). "In contrast, aphidicolin-mediated replication stress induces tumor-like microdeletions in FHIT/FRA3B." (PMID 23109895, 2012). "The immunohistochemical and biochemical data indicate that the expression of the FHIT protein is down-regulated in tumour samples and in fully transformed sarcoid fibroblast lines." (PMID 22424615, 2012). "The data we obtained document, for the first time, a reduction of FHIT protein expression in in vitro model of sarcoid-derived cell lines as well as in naturally occurring tumours." (PMID 22424615, 2012). "FHIT is a diadenosine triphosphate (Ap3A) hydrolase, and its role as a tumor suppressor has been confirmed." (PMID 23109895, 2012). "The data obtained in sarcoid tissues and sarcoid derived cell lines suggest that also in horse, as in humans, there is a possible involvement of the tumour suppressor FHIT gene in BPV induced tumours." (PMID 22424615, 2012). "Despite these findings and strong evidence that Fhit exerts tumor suppressor activity, it has been argued that deletions within the FHIT locus in transformed cells are passenger alterations rather than cancer-driving mutations." (PMID 23209436, 2012). "While further studies are needed to clarify the molecular mechanisms for FHIT protein downregulation, we suggest that this tumour suppressor gene is an important player in sarcoid transformation." (PMID 22424615, 2012). "To gain insights into the molecular mechanisms of fibroblast transformation in equine sarcoid, we analyzed tumour samples and sarcoid derived cell lines for the expression of the FHIT protein." (PMID 22424615, 2012). "While alterations in the FHIT gene have been reported in several human cancers, the putative role of this tumour suppressor gene and its epigenetic alteration in animal tumours are not well known." (PMID 22424615, 2012). "FHIT is one of the several tumour-suppressor genes on chromosome 3, when working normally, keeping any potentially cancerous cells from growing out of control." (PMID 22295218, 2011). "Consistent with its proposed function as a tumour suppressor, homozygous genomic deletions within the FHIT gene have been observed in a large number of human cancers and cancer cell lines." (PMID 22295218, 2011). "It has been reported that the expression of RASSF1 and FHIT is inhibited in NSCLC tumours, their downregulation interestingly also having been shown to be associated with promoter hypermethylation." (PMID 20736951, 2010). "In order to suppress tumor proliferation, we must avoid low level of expression of FHIT that limit microtubule assembly and restrain cell apoptosis." (PMID 18366613, 2008). "3p14.3, a region already reported to be frequently affected by LOH in RCC pathology and harboring the FHIT gene, thought to be involved in tumor suppression in many neoplasms." (PMID 18194544, 2008). "Epigenetic changes at fragile genes associated with highly expressed fragile sites, such as FHIT and WWOX, have been characterized in a number of tumours and suggested to be associated with expression of fragility." (PMID 16981993, 2006). "The same situation is likely to exist in cattle tumours, and our complete annotation of the bovine FHIT gene will allow to characterize the role of the gene in urothelial tumors, especially of the lower urinary tract." (PMID 16719907, 2006).
tumor (continued). "Tumours and matched normal lung tissues were studied using five microsatellite markers covering a total of 9 Mb and the entire FHIT locus." (PMID 15150628, 2004). "The FHIT gene is fragile in several tumour types, and FHIT knockout mice models support the idea of a haploinsufficient mechanism for FHIT-promoting tumour growth." (PMID 15150628, 2004). "In particular, human diadenosine oligophosphate hydrolase FHIT has been identified as a tumor suppressor." (PMID 15555063, 2004). "The evidence that FHIT suppresses tumorigenicity in cancer cells supports the contention that FHIT is a tumour suppressor gene." (PMID 12865924, 2003). "Four cases showed concordant loss of BRCA1 alleles in left and right cancers, four for BRCA2, seven for ATM and four cases for FHIT, suggesting possible roles for these tumour suppressor genes." (PMID 12771912, 2003). "Although FHIT alterations at the DNA and RNA level are frequent in many types of tumours, the biological and clinical significance of these changes is not clear." (PMID 10735505, 2000). "The FHIT gene is located at a chromosomal site (3p14.2) which is commonly affected by translocations and deletions in human neoplasia." (PMID 10735505, 2000). "The FHIT gene, recently cloned and mapped on chromosome 3p14.2, has frequently been found to be abnormal in several established cancer cell lines and primary tumours." (PMID 9569038, 1998). "Additionally, other integration hot spot genes in FSs have been shown to play important roles, such as FHIT, which has been identified as a tumour suppressor." (PMID 38279874, 2024). "Consistent with tumour suppressors being a major target of DOWN-paSNVs, genes with this type of mutations were significantly enriched for apoptosis-related functions (e.g. tumour suppressors CASP9 or FHIT)." (PMID 39660592, 2024). "However, much experimental evidence supports FHIT as a tumor suppressor gene, including human lung, breast, cervical, esophageal, gastric, pancreatic, and renal cancer." (PMID 38069335, 2023). "In addition, FHIT is a well-known tumor suppressor gene and covalently binds to the cofactor intracellular diadenosine triphosphate (Ap3A)." (PMID 37372369, 2023). "The tumor suppressor FHIT is well known to control cell proliferation and apoptosis." (PMID 36544755, 2022). "To define the transcriptomic signature associated with the FHITlow/pHER2high phenotype, we selected 6 FHITlow/pHER2high cases and 6 other cases in a cohort of primary tumor cells from NSCLC patients whose FHIT and pHER2 status were assessed by western blotting." (PMID 36544755, 2022). "Upregulation of the FHIT gene reported in tumor tissues was different from the blood samples." (PMID 36161592, 2022). "In vivo, FHIT expression effectively reduced tumor growth compared to the control." (PMID 36289813, 2022). "In fact, FHIT protein is a member of the HIT family of proteins that may function as tumor suppressor." (PMID 34901149, 2021). "If so, even though this tissue presents as normal, FHIT methylation may already be present, suggesting that FHIT methylation may be one of the earliest markers for tumor development." (PMID 35663592, 2021). "The fragile histidine triad (FHIT) gene (located at 3p14.2) is a bona fide tumor suppressor." (PMID 34368151, 2021). "If physicians could analyze the surrounding tissue for FHIT methylation, it will allow them to know if greater margins need to be excised to prevent future tumor outgrowth." (PMID 35663592, 2021). "In turn, one may suppose that increased methylation of FHIT may simply reflect the fact of higher tumor cells in the samples collected." (PMID 34092254, 2021). "This evidence indicates a critical role for FHIT in tumor metastasis." (PMID 34368151, 2021).